IL1B (interleukin 1 beta)
Diseases named in the same sentence as IL1B in open-access papers (continued):
Sharing a sentence is not in itself a finding about the gene and the disease.
Alzheimer disease (continued). "UB-SCG-51 administration has been shown to lower the expression of pro-inflammatory cytokines, namely Il-1β, CCL3, CCL12, and Trem2, which are mediators of glial activation and contribute to Alzheimer’s disease progression." (PMID 41007636, 2025). "Elevated levels of pro-inflammatory cytokines (IL-6, TNF-α, IL-1β, and IFN-γ) are observed in elderly individuals, leading to increased risks of atherosclerosis, type 2 diabetes, Alzheimer’s disease (AD), and osteoporosis." (PMID 40843723, 2025). "In models of Alzheimer’s disease, MCC950 effectively dampens the inflammasome activation triggered by Aβ or tau, preventing the cleavage and release of caspase-1 and IL-1β." (PMID 40260242, 2025). "In Alzheimer’s disease, the accumulation of amyloid β plaques triggers the activation of the NLRP3 inflammasome, resulting in increased production of IL-1β, which subsequently recruits immune cells and exacerbates neuronal damage." (PMID 40075143, 2025). "For instance, in Alzheimer’s disease (AD) models, amyloid-beta (Aβ) oligomers activate TLR4 on microglia, significantly increasing the production of IL-1β and TNF-α and exacerbating neuronal damage." (PMID 40934003, 2025). "In this regard, serum concentrations of some inflammatory cytokines, such as IL-1β, TNF-α, and IL-6, increase with advancing age and are highly expressed in patients with Alzheimer's disease (AD) or depression." (PMID 38300639, 2024). "EA reduces the expression of IL-1β, IL-6, and TNF-α in the hippocampus of mice with Alzheimer’s disease and acute myocardial ischemia, exerting an anti-inflammatory effect." (PMID 38629101, 2024). "SOD1 has not been reported in AAA, but when treated with hydroxyl ethanol, it inhibits Ang II-induced Alzheimer’s disease, decreases the expressing of NF-κB, P65, TNF-α, and IL-1β, and increases the conveying of SOD1, MMP9, and GCLC in mice." (PMID 37737183, 2023). "Several SASP factors, including IL-6, IL-1β, TNF-α, MMP-1, MMP-3, and MMP-10, have also been found to be elevated in the cerebrospinal fluid and serum of patients with Alzheimer’s disease." (PMID 37569663, 2023). "Specifically, the amyloid-β (Aβ) 1–42, the aberrant protein aggregation contributes to the pathogenesis of Alzheimer’s disease (AD), reduces astrocyte viability while increasing the expression of TNF-α, IL-1β, COX-2, and iNOS." (PMID 38264546, 2023). "It was also reported that levels of peripheral cytokines, such as IL-1β, TNF-α, IL-6, and C reactive protein, were significantly higher in elderly with Alzheimer’s disease." (PMID 37623235, 2023). "BBB disruption is caused by the secretion of pro-inflammatory mediators, such as IL-1α, IL-1β, IL-6, and TNF-α, due to an increase in microglia and astrocytes in Alzheimer’s disease." (PMID 35453602, 2022). "It was revealed that prolonged activation of microglia cells and the resulting overproduction of inflammatory factors, including IL-6, IL-1β, and TNF-α, were significant contributions to the development of Alzheimer's disease." (PMID 36147643, 2022). "In different clinical research, some proinflammatory factors (such as IL-6, IL-1β, and TNF-α) were reported to be overexpressed in patients with Alzheimer's disease and elderly people with mild cognitive impairment." (PMID 36147643, 2022). "Chronic neuroinflammation is one of the main drivers of Alzheimer’s disease, and JQ1 treatment has reduced the expression levels of the pro-inflammatory modulators IL-6, IL-1β, and TNF-α, suggesting promise in the treatment of neurological disorders." (PMID 35154163, 2022). "ROS also evokes Alzheimer's disease through active NLRP3, which promotes IL-1β-mediated inflammation." (PMID 35030992, 2022). "A recent study stated that donepezil incorporated into PLGA in the presence of Pluronics F68 caused a significant dose-dependent decrease in both gene and protein expression levels of IL-1β, IL-6, GM-CSF and TNF-α in Alzheimer’s disease." (PMID 34502328, 2021).
Alzheimer disease (continued). "Several cytokines (IL-1β, IL-6, TNF-α, IL-8 and IL-15) were further raised in Alzheimer’s disease with systemic infection." (PMID 33723589, 2021). "Chronic cerebral hypoperfusion accelerates Alzheimer's disease by enhancing NLRP3 inflammasome, and activating caspase-1 and IL-1β in hippocampus and thalamus of mice." (PMID 33509083, 2021). "In a study on Alzheimer’s disease, downregulation of PU.1 in BV2 cells suppressed the expression of pro-inflammatory genes, such as CCL2 and IL-1β, as well as Aif1 (also known as Iba1), a molecular marker of microglia." (PMID 34681723, 2021). "Thus, caspase-1/IL-1β may be a target for Alzheimer's disease treatment." (PMID 33509083, 2021). "Dysfunctional autophagy promotes microglial activation through regulating the production of IL1β and IL18 via NLRP3 degradation, and it contributes to neuroinflammation in Alzheimer’s disease (AD)." (PMID 33402188, 2021). "Another study showed that calycosin treatment decreased the levels of TNF‐α, interleukin (IL)‐6, IL‐1β, and MDA in acute pancreatitis (AP) mice and Alzheimer's Disease mouse." (PMID 32910538, 2020). "In addition, IL-1β is a regulator of inflammatory reactions and is involved in the stimulation of the central nervous system through cyclooxygenase-2 (PTGS2/COX2), which is involved in neurodegenerative disorders such as MS, Down’s Syndrome, Alzheimer’s disease, and HIV-associated dementia." (PMID 32102262, 2020). "Lysophosphatidylcholine (LPC) that accumulates in multiple sclerosis and Alzheimer’s disease was shown to activate both the NLRP3 and NLRC4 inflammasomes and to result in the increased IL-1β secretion seen in these patients." (PMID 31892810, 2019). "However, from an anti-inflammatory point of view, this reduction of both IL-1β and IL-6 could explain the hypothesis, proposed by Borokivova46, according to which ACh levels decrease can favor neuroinflammatory events, as observed in Alzheimer disease." (PMID 31578381, 2019). "Given that SAA is detected in Alzheimer disease and multiple sclerosis brain, together with IL-1β-immunopositive microglia, these findings propose a link between P2X7R, SAA, and IL-1β in CNS pathophysiology." (PMID 29803222, 2018). "Compared with controls, IL-1β (pooled SMD: 1.37, 95% CI: 0.06–2.68, significant heterogeneity: I2 = 96.01%) was significantly elevated in Alzheimer’s disease." (PMID 30104698, 2018). "An increase in neuroinflammatory markers such as nitric oxide, interleukin-1β (IL-1β) and tumor necrosis factor (TNF-α) has been widely reported in brains of both Alzheimer’s disease patients and transgenic AD models." (PMID 30340518, 2018). "Levels of the proinflammatory cytokines IL-6, IL-1β, and TNF-α were significantly increased in AD mice compared with WT mice, confirming that inflammation is an important characteristic of Alzheimer’s disease." (PMID 28106117, 2017). "JWH133 reduced expression of active p38 MAPK, JNK, and proinflammatory cytokines (IL-1β, IL-6, and TNF-α) induced cognitive improvement in a genetic mice model of Alzheimer's disease." (PMID 24963491, 2014). "Also down-regulated was interleukin-1β (Il1b), a well-characterized gene which produces a cytokine involved in a wide array of biological pathways most notably related to the inflammatory response and apoptosis as well as Alzheimer’s disease and type I diabetes mellitus." (PMID 23977093, 2013). "Particularly, IL-1β-dependent COX2 induction and PGE2 production have been described in glial cells in several neurological disorders, such as multiple sclerosis and Alzheimer's disease." (PMID 19660121, 2009). "For instance, a combination of N-acetylcysteine (NAC) and curcumin significantly reduced oxidative damage and neuroinflammation in models of Alzheimer’s disease by lowering neuronal apoptosis, lipid peroxidation, and pro-inflammatory cytokines such as TNF-α and IL-1β." (PMID 41002745, 2025).
Alzheimer disease (continued). "In contrast, RUT in large dose mitigated neuroinflammation by significantly reducing TNF-α and IL-1β levels, which is consistent with previous reports on RUT in neurodegenerative diseases including Alzheimer’s disease, Parkinson’s disease, and Huntington’s disease." (PMID 38512652, 2024). "An inhibitor, chemically similar to AD-16, successfully suppressed the increase of IL-1β and TNF-α levels in an Alzheimer’s disease model, suggesting that AD-16 could also modulate this pathway." (PMID 39736920, 2024). "Experimental studies have shown that diabetic patients release pro-inflammatory cytokines such as IL-1β, IL-6, and TNF-α, which may lead to neuronal death and accelerate neurodegenerative changes in Alzheimer’s disease (AD)." (PMID 39157774, 2024). "Neuroinflammation initiated by cytokines, including TNF-α and IL-1β, may be involved in BBB dysfunction and thereby promote the advancement of Alzheimer’s disease by fostering amyloid-β peptide accumulation." (PMID 39641002, 2024). "Thereby, we revealed that in the pathogenesis course of Alzheimer's disease, amyloid protein acted as the initiator, and the activation of mtDNA‐STING‐NLRP3/IL‐1β axis could induce subsequent damage to the nervous system." (PMID 37528567, 2024). "Also, Que can partially block the effect of other genes that play an important role in Alzheimer’s disease, such as tumor necrosis factor-alfa (TNF-α), interleukin 1 beta (IL-1β), and interleukin 6 (IL-6)." (PMID 37507955, 2023). "In Alzheimer’s Disease, increased IL-21 levels lead to increased expression of MHC II in spleen Mφ and secretion of a large number of pro-inflammatory cytokines such as IL-18, TNFα and IL-1β." (PMID 37628738, 2023). "The animals used were a triple transgenic Alzheimer’s disease model (3xTg-AD) in which the linalool-treated group (25 mg/kg, every 48 h, 3 months) showed a reduction in the inflammatory markers p38 MAPK, NOS2, COX-2, and IL-1β in the hippocampi and amygdalae." (PMID 37108100, 2023). "When 135 Chinese patients with Alzheimer’s disease were classified into 108 G, and 27 non-G IL1B-511 individuals, that exclusively differed in the entorhinal-cingulum axis." (PMID 37762554, 2023). "TSAIII up-regulated the acetylcholine contents, inhibited the AChE activity and decreased the expression of TNF-α and IL-1β in scopolamine-treated mice brain models, meaning that TSAIII may be across the blood–brain barrier (BBB) in Alzheimer’s disease." (PMID 36611961, 2022). "In streptozotocin-induced Alzheimer’s disease rats, the levels of neuroinflammatory markers (TNF-α, IL-1β, and IL-16) in the andrographolide-treated group were significantly reduced, and inhibition of neuroinflammation was a therapeutically important pathway for neurodegeneration." (PMID 36238575, 2022). "IL-1β is known to play an important role in the pathological process of PND, and IL-18 can influence the integrity of neurons and increase neuroinflammation in the brain, thus leading to cognitive deterioration in Alzheimer's disease." (PMID 36406365, 2022). "Cytokine-induced neuroinflammation, such as the tumor necrosis factor-α (TNF-α) and interleukin-1β (IL-1β), appear to play a role in BBB dysfunction and contribute to the progression of Alzheimer’s disease (AD) by contributing to amyloid-β (Aβ) peptide accumulation." (PMID 36142143, 2022). "In this regard, in APP/PS1 transgenic mice, a model of Alzheimer’s disease, chronic treatment with ciproxifan reduced both COX-1 and COX-2 activities, decreased the level of pro-inflammatory cytokines IL-1α, IL-1β, and IL-6, and increased the level of anti-inflammatory cytokine TGF-1β." (PMID 33918940, 2021). "For example, in the pathogenesis of Alzheimer's disease (AD), the NLRP3 inflammasome can not only damage cognition through interleukin-1β (IL-1β), which is the classic inflammatory pathway, but can also reduce Aβ removal efficiency and cause spatial memory impairment." (PMID 34666797, 2021).
Alzheimer disease (continued). "Modelling of acute systemic infection in rodents induces microglial activation and elevated pro-inflammatory cytokine production (IL-1β, IL-6 and TNF-α), and exacerbates cognitive decline, neurodegeneration, and Alzheimer’s disease-like (amyloid-β and tau) pathology in mouse models." (PMID 33723589, 2021). "Interestingly, VIP and SST are implicated in the pathogenesis of neurodegenerative diseases, including Alzheimer's disease and Parkinson's disease (PD) through reducing the production of inflammatory mediators such as TNF-α and IL-1β." (PMID 32410857, 2020). "Recent scientific studies showed that the administration of Epimedium flavonoids improved learning and memory ability through the suppression of microglia and astrocyte activation, resulting in a decrease in the production of IL-1β and TNF-α in the hippocampus of an Alzheimer’s disease mouse model." (PMID 32664577, 2020). "We found that Cl- channel inhibition blocked IL-1β release in a NLRP3-dependent model of peritonitis, and previously reported protective effects of the fenamate NSAIDs in rodent models of Alzheimer’s disease that we attributed to an effect on Cl- channel inhibition." (PMID 33216713, 2020). "One meta-analysis reported that IL-1β, IL-6, and TGF-β were elevated in PD and the work also revealed the unique inflammatory response profile in the central nervous system of patients with Alzheimer’s disease, PD, and amyotrophic lateral sclerosis." (PMID 32698474, 2020). "Their subsequent study revealed that the exaggerated inflammatory response of FAAH depletion was mediated by IL-1β specifically in the transgenic Alzheimer’s disease model but not in wild type animals." (PMID 31121907, 2019). "Our findings revealed that peripheral CRP level was not increased but IL-1β was significantly raised in elderly with Alzheimer’s disease as compared to controls before Bonferroni adjustment." (PMID 30104698, 2018). "Interleukin-1 beta (IL-1β) and its key regulator, the inflammasome, are suspected to play a role in the neuroinflammation observed in Alzheimer’s disease (AD); no conclusive data are nevertheless available in AD patients." (PMID 26939933, 2016). "NLRP3 inflammasome activation by β-amyloid in microglia is necessary for maturation of IL-1β and subsequent inflammatory events; however, the role of NLRP3 activation in Alzheimer's disease in vivo is still unknown." (PMID 24834051, 2014). "Furthermore, monocytes isolated and cultured from Alzheimer's disease patients exhibited increased gene expression of NLRP3, along with the cytokines IL-1β and IL-18, indicating heightened peripheral NLRP3-mediated immune responses in Alzheimer's disease progression." (PMID 38317229, 2024). "However, in a meta-analysis, compared with controls, only IL-1β was significantly elevated in Alzheimer’s disease but not IL-6, TNF-α or CRP and the significance did not survive Bonferroni-correction." (PMID 37467176, 2023). "Uro B intervention was found to reduce levels of IL-1β, IL-6 and TNF-α in brains of a mouse model of D-gal-induced Alzheimer disease (AD)." (PMID 35814202, 2022). "Previous studies illustrated that Th17 cells were found in the vicinity of neuritis plaques in AD brains, along with increased pro-inflammatory cytokines (IL-1β, IL-6, CXCL1, and TNF-α) in peripheral blood, which may contribute to the development of Alzheimer’s disease." (PMID 35669784, 2022). "However, the biological role of caspase-1/IL-1β in Alzheimer's disease has not been fully elucidated." (PMID 33509083, 2021). "Interestingly, both VIP and SST were reported to exert protective effects in neurodegenerative diseases, including Alzheimer's disease and PD through inhibiting the microglial activation and expression of the cytotoxic mediators, such as TNF-α, IL-1β, and prostaglandin E2." (PMID 32410857, 2020).
Alzheimer disease (continued). "However, elderly with Alzheimer’s disease only had significantly higher peripheral levels of IL-1β (p = 0.047) but not IL-6 (p = 0.138), TNF-α (p = 0.735) or CRP (p = 0.0712)." (PMID 30104698, 2018). "In models of Alzheimer disease produced by overexpression of APP/PS1 or human APP, CX3CR1 knockout results in decreased levels of pro-inflammatory cytokines Tumor Necrosis Factor (TNF) and monocyte chemotactic protein 1 (CCL2) but increased Interleukin 1-beta (IL1β)." (PMID 26469270, 2015). "However, the mechanism that initiates inactive IL-1β processing in Alzheimer's disease is not clearly defined." (PMID 24834051, 2014). "MaR1 promoted inflammation resolution by inhibiting chemotaxis, TNFα, IL1β, IL18 levels and NLRP3 inflammasome or NF-kB activation and regulating microglia activation in rodent models of Alzheimer’s disease, non-compressive lumbar disc herniation or inflammatory pain." (PMID 36670960, 2022). "While we included leptin, IL-6, IL-1β, TNF-α, and CRP, we did not assess other cytokines such as MCP-1, IL-18, or markers of microglial activation and phenotype (e.g., CD68 and sTREM2), which may play significant roles in glial reactivity in Alzheimer's disease." (PMID 40521397, 2025).